MYH7 (myosin heavy chain 7)
Diseases named in the same sentence as MYH7 in open-access papers (continued):
Sharing a sentence is not in itself a finding about the gene and the disease.
atrial fibrillation (18 papers, 2017 to 2026). A disorder characterized by an electrocardiographic finding of a supraventricular arrhythmia characterized by the replacement of consistent P waves by rapid oscillations or fibrillatory waves that vary in size, shape and timing and are accompanied by an irregular ventricular response. "Most disease-causing variants in MYH7 give rise to hypertrophy, while some variants in MYH7 can also induce atrial fibrillation before hypertrophy appears, mimicking for example LQTS." (PMID 36346469, 2023). "Since the development of atrial fibrillation was associated with risk factors such as LA enlargement, LV wall thickness, and LV outflow tract obstruction, these results suggest that patients with MYH7 mutation present with a more severe clinical phenotype." (PMID 33297970, 2020). "All three patients with pathogenic MYH7 variants were female, two of them had a mixed-apical phenotype with fibrosis on the CMR and only one had atrial fibrillation." (PMID 40428316, 2025). "For example, patients with PV in MYH7 have a higher incidence of atrial fibrillation, earlier age of onset, and more severe disease compared to those who carry PV in the MYBPC3 gene." (PMID 38540296, 2024). "Atria-Enriched GJA5, KCNA5 and NPPA, RA-Enriched HCM4, MIR100HG, REC114 and SMAD7 and Ventricles-Enriched KCNJ2, MYH7, PHLDB2, RPL2L and SLC35F1 were associated with atrial fibrillation." (PMID 34088950, 2021). "Carriers of MYH7 variants presented with a more obstructive and arrhythmogenic phenotype, demonstrating higher odds of LVOT obstruction (pooled OR range: 1.95-4.30) and a 70% increased risk of incident atrial fibrillation (HR: 1.7, 95% CI: 1.1-2.6)." (PMID 42136721, 2026). "For gene–gene comparisons, observations include a tendency to lesser maximal LV wall thickness but greater arrhythmic risk in TNNT2; restrictive physiology in TNNI339; later disease penetrance in MYBPC3 compared to MYH7; and a higher incidence of atrial fibrillation with MYH7." (PMID 38984491, 2024). "We can see that the LA_d, atrial fibrillation, age, mutation MYBPC3, and LVIDs features contributed to the increase in the predicted value for LA_d over time, while the LA_Vol and mutation MYH7 features contributed to the decrease in the predicted value for LA_d." (PMID 35107432, 2022). "However, there was a numerically higher prevalence of atrial fibrillation in the MYH7 group (60% vs. 35%, p = 0.085)." (PMID 33297970, 2020). "Furthermore, changes in the promoter region of MYH7 could be linked to the risk of developing HCM, and the patients harboring likely pathogenic or pathogenic variations in the MYH7 gene exhibited a higher incidence of developing new‐onset atrial fibrillation." (PMID 39465141, 2024).
Arrhythmia (15 papers, 2015 to 2025). Any cardiac rhythm other than the normal sinus rhythm. "Studies have found that hiPSC-CMs carrying a missense mutation (p.R663H) in MYH7 displayed the phenotype of cellular enlargement, contractile arrhythmia at the single-cell level, and dysregulation of Ca2+ cycling and elevation in intracellular Ca2+ ([Ca2+]i)." (PMID 34079803, 2021). "Summary: iPSC-derived cardiomyocytes with the MYH7 R403Q variant show conduction slowing, increased spatial dispersion of repolarization and reduced expression of some rhythmonome proteins, suggesting a biophysical basis for arrhythmia in hypertrophic cardiomyopathy." (PMID 39189070, 2024). "In patients with DCM, the incidence of a life-threatening arrhythmia (3/4 patients; 75%) in patients harboring LMNA variants was higher than that in patients harboring TTN (0/5 patients; 0%) (p = 0.008) or MYH7 (0/4 patients; 0%; p = 0.02) variants." (PMID 37904158, 2023). "Patients with LVNC usually have symptoms of heart failure, arrhythmias, and thromboembolism and always accompanied by mutations in genes such as ACTC1, MYBPC3, MYH7, SCN5A, TAZ, TBX20, and so on." (PMID 34079803, 2021). "Furthermore, downstream genes (MYH6, MYH7, TNNT2, NKX2-5, and CCND1) regulated by SFRP4 partake in ICM-related diseases like HF and arrhythmias." (PMID 40066352, 2025).
myosin storage myopathy (13 papers, 2011 to 2023). "The MYH7 gene, which encodes the slow/ß-cardiac myosin heavy chain, is mutated in myosin storage myopathy (MSM)." (PMID 37794383, 2023). "Myosin storage myopathy with typical hyalin bodies has only been described in association with MYH7 variants and is therefore considered a disease of MYH7." (PMID 36380287, 2022). "MYH7 mutations can cause two main groups of myopathies including myosin storage myopathy and Laing distal myopathy." (PMID 33298082, 2020). "Myosin storage myopathy, formerly known as hyaline body myopathy, due to the characteristic hyaline bodies on muscle biopsy, is caused by mutations in the rod domain of MYH7." (PMID 32456280, 2020). "Myosin storage myopathy and Laing distal myopathy are the two most important skeletal muscle manifestations of MYH7 mutations located in the coiled-coil rod region." (PMID 28125727, 2017). "In particular, mutations that cause myosin storage myopathy (MSM) affect the very distal end of the tail, (exons 37–40) whereas most but not all patients reported with LDM display mutations in exons 32-36 in the mid region of MYH7." (PMID 27387980, 2016).
left ventricular hypertrophy (11 papers, 2016 to 2025). Enlargement of the LEFT VENTRICLE of the heart. "In this work, we generated cardiomyocytes derived from isogenic human induced pluripotent stem cells to model the heterozygous pathogenic MYH7 missense variant, E848G, which is associated with left ventricular hypertrophy and adult-onset systolic dysfunction." (PMID 36902340, 2023). "Relationships between miRNAs and cardiac conditions such as left ventricular hypertrophy and fibrosis have already been shown across studies, including evidence for other miRNAs that overlap with the MYH7 gene serving as biomarkers for human HCM42,43." (PMID 39890868, 2025). "A study of rats demonstrated higher levels of myosin heavy chain 7 (MYH7) among male rats with left ventricular hypertrophy (LVH) compared to female rats with LVH8." (PMID 31481666, 2019). "In conclusion, the present study reports two different mutations in MYH7 and HRAS genes that independently contribute to left ventricular hypertrophy in the same family." (PMID 28002430, 2016). "In addition, cardiac-specific MCT1-knockout mice exhibited reduced ANP and MYH7 levels but partial rescue of Ang II-induced left ventricular hypertrophy." (PMID 37580825, 2023).
Ebstein anomaly (10 papers, 2014 to 2024). Ebstein's malformation is a rare congenital cardiac anomaly characterized by rotational displacement of the septal and inferior leaflets of the tricuspid valve such that they are hinged within the right ventricle, rather than as expected at the atrioventricular junction. "LVNC in those patients with Ebstein's anomaly has been associated with mutations in the sarcomere gene MYH7." (PMID 26240764, 2015). "In particular, an association with Ebstein's anomaly is recognized with an association with mutations in sarcomere gene MYH7 implicated." (PMID 26240764, 2015). "In this article the association of MYH7 mutations with Ebstein’s anomaly and LVNC and its implications for the clinical care of patients and their family members was discussed." (PMID 24668222, 2014). "A mutation in MYH7 encoding myosin heavy chain 7 was shown to cause CHDs such as Ebstein’s anomaly and septal defects." (PMID 23934094, 2014). "From a total of 140 articles published in NHJ in 2013, we selected as best basically oriented article: Ebstein’s anomaly may be caused by mutations in the sarcomere protein gene MYH7." (PMID 24668222, 2014). "MYH7 variants have been found in left ventricular non-compaction associated with bicuspid aortic valve and Ebstein anomaly." (PMID 33194928, 2020). "Variants in MYH7 have been previously reported in association with a variety of cardiac anomalies including hypertrophic, dilated and restrictive cardiomyopathies, Ebstein anomaly, and left ventricular noncompaction." (PMID 29368431, 2018). "The association between Ebstein's anomaly and LVNC may be related to mutations in the sarcomere gene MYH7." (PMID 26240764, 2015). "Recent studies have shown an association between Ebstein’s anomaly with left ventricular noncompaction (LVNC) and mutations in the sarcomeric protein gene MYH7, encoding beta-myosin heavy chain." (PMID 24668222, 2014).
left ventricular noncompaction (10 papers, 2014 to 2025). Left ventricular noncompaction (LVNC) is a rare cardiomyopathy characterized anatomically by prominent left ventricular trabeculae and deep intratrabecular recesses causing progressive systolic and diastolic dysfunction, conduction abnormalities, and occasionally thromboembolic events. "Recently, researchers have found a genetic modifier in a two-month-old girl who was diagnosed with left ventricular noncompaction (LVNC), a rare heart condition that is caused by heterozygous pathogenic variants in MYH7 and MKL2 genes." (PMID 32106447, 2020). "Variants of the MYH7 gene have been associated with a number of primary cardiac conditions, including left ventricular noncompaction cardiomyopathy (LVNC)." (PMID 36292635, 2022). "One such gene, MYH7 (OMIM #160760), is responsible for hypertrophic cardiomyopathy (HCM), dilated cardiomyopathy (DCM), left ventricular noncompaction (LVNC), Laing distal myopathy, and myosin storage myopathy." (PMID 36292635, 2022).
diabetes (8 papers, 2015 to 2025). "Significant differences or trends in Myh6 and Mhy7 with diabetes and genotype translated into a significant increase in the Myh7 / Myh6 ratio with diabetes in both genotypes, with a trend for a greater increase in KO mice (p = 0.14)." (PMID 38054572, 2023). "At week 15 of diabetes, morphometric analysis identified a 35% increase in cardiomyocyte size in MRWT mice which coincided with increased cardiac gene expression of the hypertrophy marker Myh7 (15-fold) that encodes beta-myosin heavy chain." (PMID 41332229, 2025). "However, the Myh6 and Myh7 genes were mostly comparable between WT and KO animals with diabetes, with the Myh7/Myh6 ratio demonstrating a significant increase by ~20–30 fold in both WT and KO mice with diabetes." (PMID 38054572, 2023). "The PAD gene list relates to a diverse set of human diseases, including cardiovascular (LMNA, MYH7), cystic fibrosis (CFTR), diabetes (HNF4A, IRS1) and migraine (ATP1A2)." (PMID 25611800, 2015). "Western blot validation of several proteins with high pathophysiological importance, including MYH7, HMGCS2, PDK4, and BDH1, indicated that mass spectrometry was able to qualitatively, but not quantitatively, reflect the fold changes of certain proteins in diabetes." (PMID 39539089, 2024). "When we analyzed the qPCR data from atria tissue, we observed trends for a reduction in SERCA2a in KO animals compared to WT animals regardless of diabetes status and also observed a more robust shift in the Myh7/6 ratio—both consistent of a more severe atrial dysfunction in KO diabetic mice." (PMID 38054572, 2023).
Laing distal myopathy (8 papers, 2013 to 2024). "Proline substitutions within the coiled-coil rod region of the β-myosin gene (MYH7) are the predominant mutations causing Laing distal myopathy (MPD1), an autosomal dominant disorder characterized by progressive weakness of distal/proximal muscles." (PMID 38690726, 2024). "Myopathies with scapuloperoneal, distal or limb-girdle muscle weakness including entities, such as myosin storage myopathy and Laing distal myopathy are the result of usually dominant mutations in the gene for slow/β cardiac MyHC (MYH7)." (PMID 22918376, 2013).
atrial septal defect (7 papers, 2015 to 2025). Interauricular communication is a congenital malformation characterized by a communication between the atrial chambers of the heart. "Segregation studies on dominant MYH6 and MYH7 mutations linked to congenital heart defects (CHDs) such as atrial septal defects have demonstrated variable penetrance, with several mutation carriers exhibiting no structural heart abnormalities." (PMID 40004541, 2025). "LVNC caused by MYH7 and MYBPC3 mutations often complicated congenital heart diseases (CHD), such as atrial septal defect, ventricular septal defect, Ebstein, tetralogy of Fallot, patent ductus arteriosus, patent foramen ovale, and aortic hypoplasia." (PMID 34819141, 2021). "Notably, a recent report described a 5-month-old boy with an atrial septal defect and a deletion encompassing MYH6 exons 1–26 and MYH7 exons 28–40." (PMID 40004541, 2025).
congenital myopathies (7 papers, 2014 to 2025). "Early involvement of the sartorius muscle has also been described in patients with mutations in SPEN1, RYR1, TNPO3, and MYH7, in some congenital myopathies like ACTA1, and in myofibrillar myopathies with mutations in DES or CRYAB." (PMID 35286480, 2022). "All these considerations propose a continuum in the disease spectrum related to MYH7 mutations from early onset forms with features resembling a congenital myopathy to adult forms with also proximal involvement and heart disease." (PMID 27387980, 2016). "In the congenital myopathy subgroup, 12 of 22 patients (54.5%) had disease-causing variants in RYR1 (n = 4), MYH7 (n = 3), TTN (n = 2), FHL1 (n = 1), NEB (n = 1), and SELENON (n = 1)." (PMID 40494860, 2025). "Taken together, our findings demonstrate a clear pathogenic effect of MYH7 and MYH2 mutations (associated with congenital myopathies) on myosin coiled coil structures." (PMID 37788100, 2023). "Unlikely the other, more frequent forms of congenital myopathy, our findings also propose a progressive nature of MYH7-related myopathies, and a striking difficulty in targeting the underlying molecular etiology." (PMID 27387980, 2016). "However, considering the wide phenotypic spectrum related to MYH7-myopathyes, a distinction from other congenital myopathies with distal affection is essential." (PMID 27387980, 2016).
Hypertension (7 papers, 2018 to 2025). The presence of chronic increased pressure in the systemic arterial system. "MYH7 expression was comparatively more stable across sexes, though it showed a stronger hypertension- and age-associated variation in older hypertensive females compared to younger males, further reinforcing the unique expression profile of this subgroup." (PMID 41295372, 2025). "miR-208a/b, transcribed from MYH6/MYH7, contributes to maladaptive remodeling during isoform switching toward MYH7 in hypertensive HF." (PMID 41465511, 2025). "Statistical analysis demonstrates sex-specific differences in MYH6 and MYH7 expression in healthy left ventricles, with postmenopausal females (aged > 50 years) with hypertension emerging as a distinct group." (PMID 41295372, 2025). "Of note, several of these genes (Cx43, Myh7, CSF1R, CXCR4, and CACNA1) have been reported to be associated with AF, hypertension, inflammation, cardiac and vascular remodeling." (PMID 31191333, 2019). "In contrast, significant differences in MYH7 expression were observed in male comparisons, particularly in association with age and hypertension, although these findings were not fully consistent with some prior studies." (PMID 41295372, 2025). "The availability of newly generated RNA sequencing data from a substantially larger cohort has enabled us to reanalyse the expression patterns of MYH6 and MYH7 in healthy human left ventricles, considering age, sex, and the presence of hypertension as potential modifiers." (PMID 41295372, 2025). "Collectively, these findings indicate that the combined effects of age, sex, and hypertension are most pronounced in the subgroup of older females with hypertension, where the greatest transcriptional differences in MYH6 (and occasionally MYH7) were observed." (PMID 41295372, 2025). "Finally, although our data strongly suggest that the MYH7 E848G allele is pathogenic, we cannot rule out the possibility that other clinical factors such as hypertension may act as disease modifiers." (PMID 30623132, 2018). "Compared to normotensive older males, the subgroup of older males with hypertension exhibited significantly lower MYH7 expression relative to failing male hearts, regardless of the age of the diseased group." (PMID 41295372, 2025). "When considering hypertension, there was a slight but statistically non-significant change in MYH7 expression, suggesting limited impact of these variables in males." (PMID 41295372, 2025). "For example, in patients with aortic stenosis, no significant MYH7 expression changes were observed in either sex, though that study’s cohort included individuals with varying hypertension status and age, which may have confounded results." (PMID 41295372, 2025). "Notably, 39 healthy heart samples also displayed MYH6/MYH7 ratios below this threshold, with 19 (48%) of females of higher age with hypertension and eight older females without hypertension (21%)." (PMID 41295372, 2025). "In contrast, MYH7 expression was largely stable across the hypertension-stratified comparisons, with only two minor differences detected: younger males without hypertension vs. younger males with hypertension (p = 0.022) and younger males vs. older males without hypertension (p = 0.020)." (PMID 41295372, 2025). "In summary, older females with hypertension and under the threshold represented 35% of all females in the higher age group with hypertension, 22.09% of the total number of females in the database and accounted for 49% of all control samples with MYH6/MYH7 ratios below the threshold." (PMID 41295372, 2025). "In contrast to MYH7, MYH6 expression was consistently and significantly downregulated in all comparisons, regardless of age, sex, or hypertension status." (PMID 41295372, 2025).
Hypertension (continued). "Additionally, the comparison between older females with hypertension and younger males without hypertension was unique in that both MYH6 and MYH7 were significantly differentially expressed, even after correction for multiple testing." (PMID 41295372, 2025).
Obesity (7 papers, 2015 to 2025). Accumulation of substantial excess body fat. "Overall, maternal diet-induced obesity led to an increased ratio of Myh7: Myh6 (two-way ANOVA, P = 0.0005)." (PMID 29635288, 2018). "Obesity triggered a down‐regulation of MYH6 and an up‐regulation MYH7." (PMID 31368189, 2019). "On the other hand, the lack of differences in MYH7 mRNA between the 4 groups indicates that slow-oxidative type I muscle fiber content does not vary with obesity, prediabetes or type 2 diabetes." (PMID 25803044, 2015).
restrictive cardiomyopathy (7 papers, 2014 to 2025). A type of heart disorder referring to the inability of the ventricles to fill with blood because the myocardium (heart muscle) stiffens and looses its flexibility. "Further research is needed to elucidate the pathogenesis and develop safer and cheaper approaches to diagnose MYH7-induced restrictive cardiomyopathy." (PMID 40290163, 2025).
Myocardial fibrosis (6 papers, 2022 to 2025). "In addition to the obvious myocardial fibrosis observed by histopathology, the mRNA expression of profibrotic TGF-β, CTGF, Col1a1 and Col3a1 were elevated in piglets and cardiomyocytes with MYH7 R453C mutation." (PMID 38862020, 2024).